MIR8081 (microRNA 8081)
Synonyms: hsa-mir-8081
Gene: MicroRNA gene on chromosome 9 (106,600,928 to 106,601,022, forward strand). Ensembl gene ENSG00000277889.
Homologues: Orthologues: chimpanzee MIR8081 (100% identical).